IL6 (interleukin 6)
Diseases named in the same sentence as IL6 in open-access papers (continued):
Sharing a sentence is not in itself a finding about the gene and the disease.
tumor (continued). "Notably, maslinic acid further suppresses the IL-6/JAK/STAT3 signaling cascade, regulates autophagy, and inhibits angiogenesis by impairing the formation of new blood vessels that support tumor growth." (PMID 40872208, 2025). "Finally, we assessed the effects of combined blockade of PD1 and IL-6 on macrophage recruitment in a zebrafish macrophage model and CD8+ T cell function and tumor growth in PBMC humanized mouse model." (PMID 40040705, 2025). "In order to shape the tumor microenvironment (TME), both IL-6 and IL-8 are essential." (PMID 41350724, 2025). "Additionally, statins reduce the secretion of pro‐inflammatory cytokines such as IL‐6 and CC chemokine ligand 2 (CCL2), thereby mitigating inflammation‐driven tumor progression." (PMID 40387523, 2025). "While some signaling molecules such as IL-6 were detectable, their expression did not correlate with clinical outcomes, and they were more prominent in non-tumor cell compartments." (PMID 40669378, 2025). "Consequently, high IL-6 levels and up-regulated PD-L1 expression in ESCC tissues facilitated immune evasion by tumor cells." (PMID 40433391, 2025). "Investigations into how p38 may regulate the expansion and recruitment of TAMs and MDSCs showed that p38α controls the tumor cell expression of cytokines and chemokines (e.g., CCL2, CXCL1, IL6, GM-CSF, G-CSF)." (PMID 41282257, 2025). "Unlike standard leukocytosis, PLR is driven by excessive tumour-derived cytokine secretion, predominantly granulocyte-colony stimulating factor (G-CSF) and interleukin-6 (IL-6), which promote neutrophil proliferation and a systemic inflammatory state." (PMID 40142228, 2025). "A special place for IL-6 in LC treatment, specifically its inhibition, is in K-ras-positive non-small-cell lung cancer (NSCLC), as patients with a positive K-ras LC have significant inflammation in tumor stroma." (PMID 40149994, 2025). "Beyond preclinical models, the evidence suggests that human tumor cells can secrete factors into the bone microenvironment, including IL-6 and PTH-related peptide (PTHrP), which increase the RANKL-to-OPG ratio, thereby enhancing osteolysis and promoting tumor progression." (PMID 40507804, 2025). "Additionally, TEVs induce the IL-6 and IL-17 signaling in CAFs, which promotes the secretion of pro-inflammatory cytokines in TME, thereby contributing to the progression of tumor malignancies." (PMID 40908470, 2025). "Some mediators involved in communication between tumour cells and CAFs—such as BMP-4, IGF-2, IL-6, IL-8, CXCL-1, and TGF-β—may be potential therapeutic targets." (PMID 41009413, 2025). "Inflammatory cytokines such as TNF-α and IL-6 have been shown to upregulate histone demethylases, including Jmjd3 (KDM6B), which affects the expression of genes, leading to stem-like, therapy-resistant tumour phenotypes." (PMID 40647494, 2025). "Inflammatory cytokines, such as tumor necrosis factor-α (TNF-α), interleukin-6 (IL-6), and interleukin-8 (IL-8), as well as platelet agonists like thrombin and ADP, present in the tumor microenvironment, promote platelet autophagy, resulting in platelet activation." (PMID 39852571, 2025). "IL-6 is an inflammatory mediator that also activates STAT3 and promotes tumor progression." (PMID 40759869, 2025). "Additionally, CAFs can enhance the stemness of TICs by secreting cytokines such as interleukin-6 (IL-6), which activate signaling pathways like IL-6-STAT3-NOTCH, thereby promoting tumor progression." (PMID 40568600, 2025). "Furthermore, the MMW + α-PD-L1 combination therapy promoted polarization toward anti-tumor M1-type macrophages, which secreted elevated levels of effector molecules, including IFN-γ, TNF-α, IL-6, and IL-12p70." (PMID 41383334, 2025). "Furthermore, IL-6 promotes the expression of the anti-apoptotic protein Bcl-2 through STAT3 signaling, enabling tumor cells to evade chemotherapy-induced cytotoxicity." (PMID 40563367, 2025).
tumor (continued). "One study found that IGF2BP2 may work to promote tumor growth in PTC via interactions with APOE mRNA and the IL-6/JAK2/STAT3 pathway." (PMID 40243425, 2025). "Furthermore, the expression levels of TNF-α, IL-6, IL-1β, and NOS2 in tumor tissues were enhanced following CIRT treatment compared to the control group (p < 0.001)." (PMID 40917841, 2025). "Mechanistically, ALI may affect prognosis through two pathways: firstly, high NLR reflects systemic inflammation, which promotes the release of pro-inflammatory cytokines (such as IL-6, TNF-α) and drives tumor invasion via the STAT3 pathway." (PMID 40535131, 2025). "Additionally, tumor-derived factors, such as VEGF, IL-6, and IL-10, can recruit MDSCs to the inflammatory TME, where they activate the STAT3 signaling pathway to produce more VEGF, establishing a positive feedback loop that promotes tumor angiogenesis." (PMID 40563367, 2025). "Although numerous studies have investigated the targeting of IL6 for tumor therapy, the concurrent targeting of the PIK3CAH1047R mutation and IL6 has not been documented." (PMID 40344411, 2025). "Notably, the silencing of MUC2 increases IL-6 secretion, which activates the STAT3 signaling pathway, promoting tumor cell migration, epithelial-mesenchymal transition (EMT), and metastasis." (PMID 41378310, 2025). "When the cytokine composition of the supernatant of a 48 h culture of digested Pan02 tumors, referred to as “tumor-conditioned media” (TCM), was assessed, we previously inferred that IL-6 levels were higher in TCM from mice treated with the TGFβ vaccine than in TCM from control-vaccinated mice." (PMID 39653766, 2025). "Elevated levels of pro-inflammatory cytokines, including TNF-α, IL-6, and IL-27, were detected in ALL patients, reflecting abnormal immune activation and suggesting a potential role in disease progression through tumor growth, immune evasion, or enhanced cytotoxicity." (PMID 41254398, 2025). "In addition to FFAs, increased release of cytokines such as IL‐6 and leptin by adipocytes in the TME can also lead to tumor immune escape, as observed in prostate cancer cells that are resistant to the cytotoxic action of NK cells." (PMID 39496581, 2025). "Both the stress response and tumor burden are known to induce the remodeling of adipose tissue, acute stress through activation of the sympathetic-adreno-medullar (SAM) axis with secretion of IL-6." (PMID 40229829, 2025). "Similarly, production of proinflammatory SASPs such as IL‐6 and IL‐8 is effectively curtailed by knocking out upstream regulatory molecules in HCC mouse models, which markedly attenuates tumor growth rates and progression compared with control groups." (PMID 41427020, 2025). "In fact, some factors, such as IL-6 and lactic acid, significantly promotion in the expression of Mettl3 in tumor MO-MDSC (data not shown)." (PMID 41360769, 2025). "Notably, these same malignant T cells also express LTα, whose production is induced by dysregulated JAK3/STAT5 signaling, thereby contributing to IL-6 secretion and synergizing with VEGF to support tumor vascularization." (PMID 41171472, 2025). "When overstimulated, however, this pathway stimulates proliferation of tumor cells via nuclear factor NF‐κB/JNK/ERK signaling, thereby inducing the production of cytokines, such as TNF, IL‐1α, and IL‐6, which act in a positive feedback loop to promote tumor growth." (PMID 40922674, 2025). "In senescent cells, DNA damage triggers ATM/ATR kinase activation, which phosphorylates the IKK complex to degrade IκBα, enabling nuclear translocation of the p65/p50 heterodimer—a prerequisite for SASP factor transcription (IL-6, IL-8, MMP9) that fosters a tumor-promoting inflammatory niche." (PMID 40510156, 2025). "Cytokines and growth factors within the TME, including interleukin-6 (IL-6) and transforming growth factor-beta (TGF-β), further promote the plasticity and self-renewal capabilities of progenitor cells, enabling their adaptation to the tumor niche." (PMID 40896358, 2025).
tumor (continued). "IL-6 and IL-11 influence the formation of new CAFs in the TME and promote tumor growth." (PMID 40136652, 2025). "IL-6, produced by tumor cells as well as by macrophages and fibroblasts within the TME, facilitates the growth of tumor cells and prevents apoptosis through the activation of the Janus kinase (JAK) - signal transducer and activator of transcription (STAT) 3 signaling pathway." (PMID 41346580, 2025). "This could be attributed to IL-6 use by FRCs and LECs, which also express IL-6R, although to a lower extent than the DLBCL tumor cells." (PMID 40061210, 2025). "Laboratory examinations showed elevated inflammatory markers (CRP, ESR, IL-6, and Ferritin) but no abnormalities in infection, immune, or tumor markers." (PMID 40917352, 2025). "This pathway is known to upregulate the expression of oncogenes such as c‐Myc and Bcl‐2 while enhancing the production of inflammatory cytokines like interleukin‐6 (IL‐6) and tumor necrosis factor‐alpha (TNF‐α), thereby creating a tumor‐promoting microenvironment." (PMID 40387523, 2025). "High IL6 levels correlate with a transcriptionally quiescent state in CTLs, marked by reduced expression of key activation and effector molecules, such as IFN-γ, TNFα, and granzyme B. This results in impaired cytotoxic activity against tumor cells." (PMID 40427188, 2025). "Here we have identified IL-6 as a CAF-derived factor that mediates crosstalk between the tumor stroma and tumor cells in ILC, leading to activation of the JAK/STAT3 signaling pathway, and increased migration, invasion and dissemination of ILC cells in zebrafish embryos." (PMID 40597443, 2025). "Finally, miR-21-5p expression appears to be dynamically regulated by proinflammatory cytokines such as IL-6 and TGF-β, suggesting that inflammatory cues within the tumor microenvironment further enhance its induction." (PMID 41465544, 2025). "By interrupting the IL-6 → STAT3 or PI3K → immunosuppressive circuits, we might convert an immune-cold tumor into an immune-responsive one." (PMID 41374963, 2025). "For MICA/B and PD-L1 measurement, tumor cells were co-cultured with CM from M1 macrophages, with or without anti-IL-1β, anti-IL-6, and anti-TNF-α antibodies." (PMID 40369131, 2025). "In line with this, we found that levels of Il-6 mRNA were not affected in peripheral tissues (liver and intestine) of C26 mice, but were almost doubled at the tumor site in the Cx group compared to pre-Cx group." (PMID 40124481, 2025). "Besides, it had a 76% reduction in tumor volume, significantly increased the antioxidant activity (SOD, CAT, GSH), decreased the levels of inflammatory biomarkers (IL-6, COX-2, NF-κB), and markedly downregulated the EGFR expression (p < 0.0001)." (PMID 41599143, 2025). "While initially tumor-suppressive by halting malignant transformation, senescent cells develop a senescence-associated secretory phenotype (SASP), releasing inflammatory cytokines (IL-6, IL-8), growth factors (TGF-β), and proteases that remodel the tumor microenvironment (TME)." (PMID 40510156, 2025). "The administration of arjunolic acid in this study led to a significant reduction in pro‐inflammatory cytokines such as TNF‐α, IFN‐γ, and IL‐6, along with lower levels of VEGF (a key factor in tumor angiogenesis) and a marked increase in anti‐inflammatory cytokine IL‐10." (PMID 40908716, 2025). "Importantly, tumor inflammatory pathways, including IL2-STAT5 signaling, IL6-JAK-STAT3 signaling, and interferon-alpha response, were predominantly enriched in the high PCA score group." (PMID 41445790, 2025). "Indeed, pro-inflammatory cytokines, such as the IL-1 family, IL-6, and TNF-α, are key players in creating chronic inflammation in the tumor context." (PMID 40650089, 2025). "In addition, SDA and its metabolites can inhibit nuclear factor kappa B (NF-kB), which reduces the expression of inflammatory cytokines (such as IL-6 and TNF-α) that contribute to tumor development." (PMID 40507897, 2025).
tumor (continued). "In addition, CD70 expressed in fibroblasts amplifies cytokine and chemokine production, including IL6 and MCP-3, which not only support cSCC growth, but also modulate the tumor microenvironment." (PMID 41510255, 2025). "In addition, CAFs release cytokines/chemokines (such as IL-6, IL-8) that inhibit autophagy in OCC, thereby promoting tumor transfer." (PMID 40104498, 2025). "LOX enhances the hypoxia adaptation of tumour cells by upregulating HIF‐1α, which in turn activates the NF‐κB pathway and drives the secretion of inflammatory factors (e.g., IL‐6, TNF‐α), further recruiting immunosuppressive cells (e.g., TAMs, MDSCs) to form a pro‐cancer TME." (PMID 40179101, 2025). "In particular, MSCs isolated and characterized from malignant tissues of patients with HNSCC constitutively produced high amounts of molecules such as IL-6, IL-8 and SDF-1α and were able to enhance growth of FaDu xenografts likewise BM-MSCs when coinjected with tumor cells in nude mice." (PMID 39930439, 2025). "In a bilateral tumor model, untreated distal tumors exhibited growth suppression when the primary tumor received “CP+-CpG + Light” therapy, accompanied by elevated IFN-γ, IL-6, and TNF-α levels in tumor tissues." (PMID 40363042, 2025). "Moreover, previous studies had shown that B7H3 can upregulate IL-2, IL-6, IL-17, and TGF-β1 levels while diminishing IFN-γ production, and B7H3 antibodies can promote the infiltration of CD8+ T cells in the tumor microenvironment." (PMID 41291854, 2025). "These cells facilitate tumor growth by producing ECM components and secreting a variety of soluble mediators, including transforming growth factor-β (TGF-β), interleukin (IL)-6, and hepatocyte growth factor (HGF), which promote cancer cell proliferation, invasion, and immune modulation." (PMID 41244711, 2025). "In contrast, P.g. delays tumor growth induced by OSC-20 human OSCC cells injected subcutaneously in nude mice while provoking resistance to paclitaxel, likely due to cytokine modulation, particularly IL-6." (PMID 40924302, 2025). "Macrophages are the primary producers of numerous molecules that facilitate tumor angiogenesis, such as VEGFA, CXCL8 (chemokine (C-X-C motif) ligand 8), PlGF (placental growth factor), IL-1β (interleukin-1 beta), IL-6 (interleukin-6), TNF (tumor necrosis factor), MMPs, and cathepsins." (PMID 40940953, 2025). "Furthermore, we found that the levels of IL6, as well as the phosphorylation of JAK1 and ACAP4 at Tyr843, were significantly greater in tumor tissues from HCC patients than in adjacent tissues." (PMID 39744421, 2025). "However, as tumors progress, cytokines such as IL-6, IL-10, TGF-β1, and G-CSF, neutrophils are polarized to the pro-tumor N2 phenotype, which exhibits immunosuppressive properties." (PMID 41200171, 2025). "Here, we found that, compared with control counterparts, IL6 was significantly upregulated in the serum and tumor tissues of HCC patients, with a negative correlation with the prognosis of patients." (PMID 39744421, 2025). "Furthermore, acetate engaged G protein-coupled receptor 43 (GPR43) on hepatocytes, inhibiting the IL-6/JAK1/STAT3 pathway, inducing apoptosis of NAFLD/HCC tumor cells, preventing tumor formation, and enhancing intestinal barrier function." (PMID 40165786, 2025). "In terms of tissue invasion and distant metastasis, TAMs enhance the invasiveness and migratory capacity of tumor cells by activating the EMT, particularly through the activation of toll-like receptor-4 and the subsequent secretion of cytokines such as IL-6 and TNF-α." (PMID 40098971, 2025). "Furthermore, research has found that the deletion of certain Y chromosome genes activates inflammation-related pathways (e.g., IL-6 and CCL2), promoting tumor development." (PMID 40248204, 2025).
tumor (continued). "Finally, similar to MSC, we found that other components of the OS microenvironment ˗ specifically normal human osteoblasts or tumour-infiltrating monocytes ˗ can also promote axonal outgrowth, through mechanisms involving BDNF and IL-6." (PMID 41029717, 2025). "Furthermore, the pro-tumor factors secreted by M2 macrophages (such as VEGF and IL-6) promote cancer cell proliferation while assisting cancer cells in invading and metastasizing by remodeling the extracellular matrix (such as by secreting MMP-9)." (PMID 40109347, 2025). "This dual modulation of inflammatory mediators—suppressing chronic inflammation (IL-1β, IFN-γ) while inducing acute immune activation (IL-6, TNF-α)—may reprogram the tumor microenvironment toward an immune-permissive state." (PMID 41401147, 2025). "This chronic inflammatory state promotes the release of cytokines (e.g., IL-1β, IL-6, IL-10, IL-18, TNF-α) and growth factors that facilitate tumor cell proliferation, invasion, and angiogenesis, while simultaneously impairing effective immune surveillance against malignant cells." (PMID 41114747, 2025). "The promotion of IL-6 release and inflammation following RFA treatment may contribute to the proliferation, migration, and invasion of tumor cells through various mechanisms." (PMID 41403696, 2025). "Beyond the cytokine IL-6, IL-8 plays a critical and non-redundant role in the tumor microenvironment by promoting the growth and recruitment of neutrophils." (PMID 41254689, 2025). "In particular, reduced TRPM5 activity leads to an increase in cytosolic Ca2+ concentration, which stimulates proliferative pathways and the production of inflammatory cytokines such as IL-6 and CXCL10, with particularly marked effects at the invasive edges of the tumor." (PMID 40507957, 2025). "In these conditions, unlike the tumor microenvironment, IL-6 is a true marker exclusively for M1 macrophages." (PMID 40918453, 2025). "Genes associated with B cell trafficking (CXCL3, CXCR5, CCR6, and CCL20) and IFN-γ downstream chemokines (CXCL9, CXCL10) were upregulated, while pro-inflammatory genes (IL-2, IL-6, IL-8) were not, indicating tumor microenvironment remodeling." (PMID 40700292, 2025). "IL-6 promotes the activation of signal transducer and activator of transcription 3 (STAT3) signaling in both tumor cells and infiltrating immune cells, leading to increased proliferation, survival, and expansion of regulatory immune subsets such as Tregs and MDSCs." (PMID 41179287, 2025). "Cembranoids suppress TGF-β-induced IL-6 while sparing canonical Smad signaling, indicating selective inhibition of non-Smad, tumor-promoting inflammation." (PMID 41373438, 2025). "Additionally, DNTTIP2 is involved in the IL6/JAK/STAT3 signaling pathway, which is key to tumor growth and immune evasion." (PMID 40577282, 2025). "Additionally, they produce a variety of cytokines, chemokines, and growth factors, such as TGF-β, IL-6, and VEGF, which facilitate tumor cell proliferation, angiogenesis, and immune evasion." (PMID 40075700, 2025). "It is thought that IL-6/JAK/STAT pathways could affect the proliferation, survival, and metastasis of cancer cells, while blocking the pathway in animal studies reduced the tumor burden." (PMID 40427164, 2025). "CAFs release substantial amounts of growth factors and proinflammatory cytokines, such as transforming growth factor-β (TGF-β), interleukin-6 (IL-6), and CC-chemokine ligand 2 (CCL2), which recruit immune cells, particularly immunosuppressive cells, into the tumor stroma, promoting immune evasion." (PMID 40430018, 2025). "Putting it together, our findings did not support Fusobacterium-associated M2 macrophage polarization in vivo, nor did they indicate that Fusobacterium promotes IL6/STAT3-mediated c-myc gene expression in tumor biopsies." (PMID 40895532, 2025). "Inhibition of IL-6 or its downstream pathways, including STAT3, could inhibit POSTN secretion and reduce tumor aggressiveness." (PMID 40426238, 2025).